HIF1A (hypoxia inducible factor 1 subunit alpha)
Diseases named in the same sentence as HIF1A in open-access papers (continued):
Sharing a sentence is not in itself a finding about the gene and the disease.
tumor (continued). "In OSCC, a high HIF-1α expression is associated with glucose metabolism, increased aggressiveness and tumor progression." (PMID 38474362, 2024). "We showed that new strategies are tested to overcome the GBM-associated hypoxic-induced activation of tumor growth factors, including HIF-1α and VEGF, and immunosuppression, with promising results." (PMID 39055895, 2024). "They revealed that HIF-1α expression was higher in cancer tissues than in surrounding normal tissues, and that higher HIF-1α expression was associated with tumor cell motility, recurrence, and poor prognosis." (PMID 38727811, 2024). "The negative regulation of SOD3 in a tumor is associated with its progression through the pro-oncogenic NF-κB and HIF-1α signaling pathways, as has been observed." (PMID 39589950, 2024). "Overexpression of HIF-1α has been shown to be closely associated with poor prognosis, increasing tumor growth, vascularization, and metastasis." (PMID 38339244, 2024). "Nanoparticles 55@HSA (5 mg kg−155) caused a strong reduction of tumor mass associated with downexpression of PD-L1 and HIF-1α in the tumor tissue." (PMID 39138299, 2024). "Of the different HIF proteins, HIF-1α overproduction in BC patients significantly promotes tumor metastasis and is associated with unfavorable clinical outcomes as well as mortality." (PMID 39609700, 2024). "HIF-1α is a pivotal stress-responsive transcription factor that responds to low oxygen levels, and its expression is closely linked to tumor development and lymphangiogenesis." (PMID 38791180, 2024). "Conversely, silencing HIF-1α expression using RNA interference significantly improved tumor susceptibility to VSV-mediated oncolysis." (PMID 39861805, 2024). "The overexpression of HIF1A has been linked to increased tumor aggressiveness and resistance to conventional therapies." (PMID 39458948, 2024). "This dynamic process underlines the role of HIF-1α in regulating EZH2-mediated epigenetic modifications that contribute to tumor cell dissemination and metastasis." (PMID 38911968, 2024). "The pro-cancer effects of HIF-1α are characterized by promoting tumor angiogenesis and tumor-associated immune escape, inducing metabolic reprogramming and drug resistance." (PMID 39062453, 2024). "HIF‐1α induces increased expression of triggering receptor expressed on myeloid cells‐1 (TREM‐1) on tumour‐associated macrophages (TAMs), impairing the cytotoxic function of CD8+ T cells and inducing CD8+ T cell apoptosis." (PMID 38935536, 2024). "The lncRNA MALAT1 has also been associated with HIF-1α modulation in breast cancer, affecting tumor invasion and metastasis." (PMID 38279330, 2024). "Loss of VHL stabilizes the protein levels of the hypoxia­inducible factors, HIF1α and HIF2α, resulting in oxygen loss and tumor cell pseudohypoxia." (PMID 38191389, 2024). "It interacts with HIF-1α, facilitating its K63-linked polyubiquitination and promoting tumor angiogenesis." (PMID 38169510, 2024). "Exosomes containing EMT-inducers (TGF-β, hypoxia-inducible factor 1 alpha (HIF1α), and β-catenin) are taken up by recipient cells in the tumor stroma, causing cellular changes, and resulting in facilitated EMT in epithelial cells." (PMID 38231464, 2024). "Loss of function mutations in these tumor-suppressive genes were negatively correlated with HIF-1α target genes (CA9, VEGFA, and LDHA) in glioma." (PMID 38534356, 2024). "HIF-1α expression has been shown to negatively correlate with major histocompatibility complex (MHC) class I chain-associated genes which are essential for tumour antigen presentation and immune recognition." (PMID 38352889, 2024).
tumor (continued). "Recent studies have revealed that the tumor reprogramming of metabolism is associated with the persistent high expression of glycolysis-related genes, with HIF-1α and c-Myc are considered as the most critical glycolysis-promoting transcription factors." (PMID 39003255, 2024). "HIF1α is a transcription factor that gets activated under hypoxia condition which is associated with tumor microenvironment." (PMID 38666828, 2024). "HIF‐1α is a critical transcriptional regulator mediating cellular responses to hypoxia, implicated in the pathogenesis and angiogenesis of tumours, and extensively involved in the modulation of both innate and adaptive immune responses." (PMID 39107958, 2024). "Increased CSN5 expression is sufficient for aerobic HIF-1α stabilization, and its overexpression is associated with tumor progression." (PMID 38791951, 2024). "Meanwhile, R2* has been identified as an independent risk factor for predicting HIF-1α over expression by multivariate analysis, indicating its potential and distinctiveness in assessing the anoxic microenvironment of tumor." (PMID 39723370, 2024). "On the other hand, MIL-101/ACF@CCM effectively suppresses the expression of HIF-1α, thereby improving the hypoxic conditions of the tumor microenvironment and further making up for the deficiency of single CDT therapy." (PMID 38794281, 2024). "Loss of HIF1α in T cells impairs their tumor killing capacity and renders tumor-bearing mice resistant to ICBs, which can be overcome by acetate supplementation both in vitro and in vivo." (PMID 39477954, 2024). "Numerous studies have identified that HIF1α is implicated in tumor metabolism, angiogenesis, drug resistance, immune escape, and especially invasion-metastasis cascade by activating transcription of both coding RNAs as well as non-coding RNAs." (PMID 38485986, 2024). "It has been observed by another research team that low HIF-1α expression is associated with elevated IFNG expression in tumor-infiltrating NK cells in humans." (PMID 38808131, 2024). "The plethora of excreted factors, proteins, etc., by HIF-1α subsequently induces angiogenesis, but the leaky vasculature of tumour endothelial cells (TECs) causes a corresponding decrease in angiogenesis, and the cycle arises." (PMID 38399237, 2024). "After being attracted to tumour tissues, M‐MDSCs can differentiate into tumour‐associated macrophages if HIF‐1α is upregulated in the TME." (PMID 38450975, 2024). "HIF‐1α was stabilized as a result of VHL inactivation and it was strictly associated to RCC, therefore, HIF‐1α expression was observed only in tumor organoids." (PMID 38923304, 2024). "The hypoxic tumor microenvironment that stabilizes the HIF-1α is responsible for the great loss of ER-α protein in BC cell membranes by the manner of proteolysis rather than inhibiting its transcription." (PMID 39167288, 2024). "The upregulated pathways of NK and TCR, as well as the downregulated HIF‐1α signaling pathway, were associated with the anti‐tumor effect of PDEH." (PMID 39118566, 2024). "In mouse cSCC tumor models, loss of Hif1α in the epidermis reduced tumor formation in response to UV." (PMID 38982038, 2024). "Future works that determine if LMP2A activates mTOR/ p70 S6K/4E-BP1 to enhance HIF-1α and ATP production in pre-malignant cells would be important to understand the contribution of this pathway to tumor development in EBV-associated tumors." (PMID 38612754, 2024). "Some studies also reported that HIF1α is responsible for the polarization towards the M2-like phenotype of tumor-associated macrophages, promoting tumor growth." (PMID 39543383, 2024). "The ability of HIF1α or HIF2α deficient myeloid cells to influence tumor growth was tested using the subcutaneous LLC syngeneic mouse model." (PMID 38422022, 2024). "Elevated HIF1α protein levels have been reported in numerous human cancers and are closely linked with tumor malignancy." (PMID 38339062, 2024).
tumor (continued). "HIF-1α can cause angiogenesis, anaerobic glycolysis of tumor cells, tumor cell proliferation, invasion, and migration, as well as multidrug resistance." (PMID 39167288, 2024). "Succinate and ROS were known to enhance the function of HIF-1α, which is associated with tumor promotion." (PMID 38880883, 2024). "Activated HIF1A recruits M2-type tumor-associated macrophages (TAMs), aiding chemoresistance in GC35." (PMID 38877062, 2024). "SLC7A11, a member of the amino acid transporter SLC7 family, is induced by IL‐1β to upregulate PD‐L1 and CSF1 through αKG/HIF1α axis, leading to infiltration of tumor‐associated macrophages and myeloid‐derived suppressor cells and promoting metastasis of HCC." (PMID 39041652, 2024). "Accordingly, HIF1α, has been reported to activate tumour-associated MDSCs resulting in the suppression of both antigen-specific and non-antigen-specific T-cells through the expression of PD-L1." (PMID 36691794, 2023). "It was previously reported that the hypoxic tumor microenvironment impairs the maturation and NK cells activity and that HIF1A deficiency in tumor-infiltrating NK cells enhances their tumor-suppressive effects." (PMID 38035113, 2023). "Tumor-associated macrophages respond to hypoxia to induce HIF-1α, which results in lymphangiogenesis." (PMID 38085375, 2023). "HIF-1α deficiency has been shown to cause reduced activation and tumor infiltration by the CD8+ cytotoxic T cells, leading to compromised tumor cell killing and alteration of tumor vascularization." (PMID 37031300, 2023). "Although HIF-1α overexpression was found to be significantly associated with tumor size, associations with other clinicopathologic parameters were not noted." (PMID 36766555, 2023). "Among the mediators in tumor-related angiogenesis in response to hypoxia caused by arterial embolization, another key molecule is HIF-1α." (PMID 37374319, 2023). "Several studies have shown that high HIF-1α levels are associated with larger tumor size, higher tumor grade, decreased overall survival, and resistance to chemotherapy and radiation therapy." (PMID 37345074, 2023). "Yen-An Tang found that inhibition of HIF1α can reverse chemotherapy resistance caused by tumor microenvironment." (PMID 37790761, 2023). "Consistently, knockdown of RP11‐367G18.1 variant 2 significantly reduced the tumor growth of xenografted RCC cells overexpressing constitutively active HIF‐1α." (PMID 36847128, 2023). "It is well known that high VEGFA and HIF-1α expression levels are associated with a worse outcome in a wide array of malignancies through promoting tumor angiogenesis." (PMID 36678795, 2023). "Carbonic anhydrase IX (CA IX) is a tumor-associated, cell surface glycoprotein, the expression of which is primarily induced by the HIF-1α transcription factor during hypoxia." (PMID 36901756, 2023). "As a subunit of HIF-A, HIF1A has been implicated as a tumor promoter gene, which was overexpressed in tumors of the ovarian, bladder, and prostate." (PMID 36994412, 2023). "In patients with gastric cancer, chronic hypoxia results in HIF-1α activation, which is highly associated with an aggressive tumor phenotype and poor prognosis." (PMID 37747648, 2023). "Activation of the HIF‐1α pathway is associated with aggressive tumor characteristics and unfavorable clinical outcomes in various cancer types." (PMID 37701531, 2023). "In vitro and in vivo studies have demonstrated that the inhibition of this miRNA impaired tumor progression by increasing apoptosis and suppressing angiogenesis through the inhibition of the HIF-1A/VEGF/VEGFR2-associated signaling pathway." (PMID 37444533, 2023). "It was shown that in the hypoxic environment, HIF-1α is involved in the hypoxic response and activates hundreds of genes associated with the tumor vasculature and tumor cell adaptation to the hypoxic environment." (PMID 37240068, 2023).
tumor (continued). "Due to the rapid growth of tumors, blood vessels formation near tumor center is commonly deficient, leading to insufficient energy supply of ischemia and hypoxia, and increasing hypoxia inducible factor-1α (HIF-1α) expression." (PMID 37391451, 2023). "Studies have shown that sustained HIF-1α activation promotes tumor-associated angiogenesis, as well as tumor cell survival and proliferation." (PMID 36747531, 2023). "HIF-1a has been associated with an increase in tumor angiogenesis through the activation of VEGF and platelet-derived growth factor (PDGF) pathways." (PMID 37370846, 2023). "The tumor tissues were then subjected to immunohistochemical staining to detect proteins associated with the cell cycle, Ki-67, and the HIF-1α/LDHA pathway." (PMID 37730658, 2023). "Studies have shown that over expression of HIF-1α in EC promotes lymph node metastasis and myometrial invasion of tumour cells, which is significantly associated with poor prognosis of EC." (PMID 37965452, 2023). "In hypoxic tumor cells, the central hypoxia-inducible factor HIF-1α transactivates CD274, the gene encoding PD-L1 protein, and leads to tumor immune escape from CD8+ cytotoxic T cells." (PMID 36747292, 2023). "High HIF-1α expression was significantly associated with large tumor size, grade III cases, positive LVI, stage III cases and high Ki-67 expression (p = 0.027, 0.027, 0.017, 0.017, 0.001 respectively)." (PMID 36939902, 2023). "HIF-1α has been shown to promote the differentiation of myeloid-derived suppressor cells at the tumor site toward tumor-associated macrophages (TAMs) to support tumor progression." (PMID 36901858, 2023). "HIF-1α, coupled with the expression of target genes encoding glycolytic enzymes and the pro-inflammatory cytokine IL-1β, can block tumor growth and survival and exacerbate inflammation." (PMID 37492564, 2023). "Stromal-specific BRCA1 depletion causes tumor growth by inducing HIF-1a levels, increasing the ketone body, and activating autophagy/mitophagy." (PMID 38067169, 2023). "HIF-1α is under severe cellular control as its exceptional activation is always associated with tumorigenesis and tumor progression." (PMID 36747531, 2023). "Nevertheless, in this study, we observed effective suppression of HIF‐1α, proliferation, and tumor growth in both LKB1‐deficient (A549) and LKB1‐proficient (H1299) NSCLC cells and tumors." (PMID 37584455, 2023). "In tumor-associated macrophages (TAMs), lactate induces HIF-1α stabilization and the HIF-1α-dependent/independent expression of M2-polarizing genes (i.e., Arg and VEGF) that promote an M2-like phenotype." (PMID 37444583, 2023). "In accordance, in hypoxic environment the HIF1α transcriptional networks underlay tumor occurrence and development." (PMID 37813876, 2023). "Hypoxia is an essential hallmark of solid tumors and HIF1α is a central regulator of tumor cell adaptation and survival in the hypoxic environment." (PMID 37813876, 2023). "For example, PMP treatment induced the expression of HIF-1A, which is known to promote the interaction between neoplastic B cells and their microenvironments, induces the generation of tumor-associated macrophages (TAM), and participate in drug-resistance." (PMID 37441073, 2023). "The loss-of-function mutations in this tumor-suppressor gene result in the accumulation of HIF1α/2α, eventually leading to overexpression of VEGF/PDGF, AXL, and MET, among others." (PMID 37400554, 2023). "A statistically significant association between HIF-1α overexpression and increased tumor size was also noted using the same cut-off for positivity (HS120)." (PMID 36766555, 2023). "Tumor progression and angiogenesis are usually influenced by hypoxia, a condition mediated by hypoxia-inducible factor 1-alpha (HIF1α) that, when associated with hypoxic condition, can modulate VEGF, which is essential for neovascularization." (PMID 37445657, 2023).
tumor (continued). "IPA for the xenograft stroma revealed the activation of pathways associated with HIF1α signaling, movement of tumor cells and endothelial cells, and angiogenesis." (PMID 37980563, 2023). "A specific metabolic gene signature was identified as a hallmark of BRAF-mutated tumours, which display a glycolytic phenotype, characterised by enhanced glucose uptake, lactate efflux and increased expression of Hif-1α-modulated glycolytic genes." (PMID 37198319, 2023). "Spearman rank test was conducted to discover the association between OCN and HIF‐1α in tumor tissues." (PMID 36971046, 2023). "This is because HIF-1α is an important transcriptional factor that modulates the production of numerous key genes linked to tumor angiogenesis, including VEGF and PDGF-BB." (PMID 37626752, 2023). "HIF-1α is also involved in the transformation of tumor-associated macrophages (tam) from antitumor phenotype (M1) to tumor-causing phenotype (M2)." (PMID 37921852, 2023). "Von Hippel–Lindau (VHL) is a tumor suppressor that leads to the ubiquitination and destruction of hypoxia-inducible factor (HIF)1α and HIF2α (HIF1/2α) in normoxic conditions and is mutated in 64% of ccRCC cases." (PMID 37568390, 2023). "A statistically significant association was found between HIF-1α overexpression and increased tumor size (T status) using the weighted histoscore (median value HS120) as a cut-off for positivity (p = 0.046; χ2-test)." (PMID 36766555, 2023). "STAT3 induces VEGF expression in the association of hypoxia-inducible factor 1-alpha (HIF1A) to promote tumor angiogenesis." (PMID 37860678, 2023). "The obtained H-MnO2-PEG/TP nanoshells decomposed in the acidic tumour microenvironment, releasing the loaded drugs (TP) causing reduced tumour hypoxia and hypoxia-inducible factor-1α (HIF-1α) expression." (PMID 38112935, 2023). "The robust glycolytic activity observed in tumor cells is closely associated with the dysregulation of signaling molecules, particularly the aberrantly activated hypoxia-inducible factor 1-alpha (HIF1α) and c-Myc." (PMID 38099309, 2023). "HIF1α is a crucial regulator of glucosemetabolism in tumor cells and is known to connect numerous important pathways to glycolysis.Additionally, HIF1α is associated with redox homeostasis." (PMID 37108312, 2023). "HIF1α is a transcription factor associated with hypoxic stress and regulates several oncogenes to maintain and promote blood vessel formation and tumor growth in PCa." (PMID 36841806, 2023). "Our results showed that high expression levels of BIRC5, FLT, and HIF1A were more clearly associated with primary NSCLC tumor progression and metastasis than normal samples." (PMID 37509650, 2023). "A common feature of tumour tissues is hypoxia caused by oxygen diffusion limitations leading to HIF-1α stabilisation." (PMID 36928373, 2023). "Consistently, knockdown of RP11-367G18.1 variant 2 or YY1 suppressed the tumor growth of xenografted FADU cells overexpressing HIF-1α (ΔODD), suggesting that hypoxia-induced tumorigenicity was attributable to the RP11-367G18.1 variant 2–YY1 complex." (PMID 37941005, 2023). "Hypoxia is a key factor in promoting tumour growth through cell signalling involving HIF-1α and its target VEGF, which are associated with poor clinical outcomes in CRC." (PMID 38137047, 2023). "Previously, in PDAC, it was reported that HIF-1α activation by tumor hypoxia causes secretion of sonic hedgehog (SHH) by cancer cells, which stimulates deposition of fibrous tissue by stromal fibroblasts." (PMID 38028629, 2023). "Among all tumor types in TCGA, the most common mutated genes are HIF1A and SLC16A7, which accounts for 21% in all samples." (PMID 37122693, 2023). "Fumaric acid has been implicated to inhibit the degradation of HIF-1α in tumor cells so as to overcome hypoxia in several cancer types." (PMID 38060623, 2023). "HIF-1α overexpression is a tumor-specific finding associated with increased tumor size and carries a potential diagnostic role." (PMID 36766555, 2023).